DPP4 (dipeptidyl peptidase 4)
Diseases named in the same sentence as DPP4 in open-access papers (continued):
Sharing a sentence is not in itself a finding about the gene and the disease.
myocardial infarction (73 papers, 2011 to 2025). Gross necrosis of the myocardium, as a result of interruption of the blood supply to the area, as in coronary thrombosis. "In mouse models, sitagliptin improved capillary collateralization in the setting of hind limb ischemia, and DPP4 inhibition has been shown to attenuate endothelial cell loss in the heart following acute myocardial infarction in mice." (PMID 37300400, 2023). "SGLT2 inhibitors have been demonstrated to reduce the risk of composite outcomes, including myocardial infarction, stroke, and all-cause mortality, when compared to dipeptidyl peptidase-4 inhibitors." (PMID 37891550, 2023). "DPP-4 deficiency and DPP-4 inhibition by sitagliptin has been found to reduce mouse mortality due to a lower rate of myocardial infarction." (PMID 33401457, 2021). "Dipeptidyl peptidase 4 inhibitors and glucagon-like peptide-1 agonists were associated with a lower risk of myocardial infarction (MI) than were sulfonylureas (odds ratio [95% credible interval] 0.41 [0.24–0.71] and 0.48 [0.27–0.91], respectively)." (PMID 29150631, 2017). "Treatment with DPP4-inhibitors was suggested to reduce the risk of CV events (particularly myocardial infarction) and all-cause mortality in patients with T2DM." (PMID 27078018, 2016). "Patients who recover from a myocardial infarction express high DPP4 levels on their MNCs, which is associated with a decreased heart function." (PMID 25852751, 2015). "A prominent GLP-1 level in DPP4-deficient rats contributed to the resistance of endotoxemia and myocardial infarction." (PMID 24416433, 2014). "Linagliptin attenuates cardiac dysfunction after myocardial infarction in DPP-4 deficient rats." (PMID 33803842, 2021). "In addition, polymorphism in the DPP4 gene was a risk factor for a myocardial infarction (MI) in patients of European ancestry with atherosclerosis." (PMID 27111895, 2016). "Similarly, in another ethnic group of 875 angiographically-proven CAD patients of European origin, a single-nucleotide polymorphism (SNP) in the DPP4 gene, which leads to decreased plasma DPP4 levels, was associated with increased risk of myocardial infarction." (PMID 34389003, 2021). "Dipeptidyl peptidase-4 (DPP4) regulates blood glucose levels and inflammation, and it is also implicated in the pathophysiological process of myocardial infarction (MI)." (PMID 28587613, 2017). "That DPP4 inhibition is a feasible treatment modality for the improvement of MNC homing is strengthened by the observation that in DPP4 deficient mice the mobilization capacity of the progenitor cell population was restored after myocardial infarction, and angiogenesis improved." (PMID 25852751, 2015). "Treatment with the DPP-4 inhibitor vildagliptin improved the survival rate after acute myocardial infarction by restoring the autophagic response in OLETF rats, a model of T2DM." (PMID 37760498, 2023). "In a mouse model of acute myocardial infarction, Kubota and others found that DPP4 inhibition reduced infarct size, improved cardiac function, and reduced apoptosis." (PMID 37300400, 2023). "Some polymorphisms have been associated with DPP4 and apolipoprotein B concentration, T2DM, and myocardial infarction in CAD patients." (PMID 35885620, 2022). "Occurrence of cardiovascular death, myocardial infarction and ischaemic stroke were also similar between patients treated with DPP4 inhibitors and placebo." (PMID 34097240, 2022). "We observed that patients receiving sulfonylureas had a small increased hazard of myocardial infarction and eye disorders when compared with patients receiving DPP-4 inhibitors in the meta-analysis." (PMID 30646124, 2018). "Patients treated with sulfonylureas compared with DPP-4 inhibitors had a small increased consensus hazard ratio of myocardial infarction (1.12; 95% CI, 1.02-1.24) and eye disorders (1.15; 95% CI, 1.11-1.19) in the meta-analysis." (PMID 30646124, 2018).
myocardial infarction (continued). "Sulfonylureas had a small, higher observed hazard of myocardial infarction and eye disorders compared with DPP-4 inhibitors in the meta-analysis." (PMID 30646124, 2018). "Results have been mixed with respect to the role of DPP-4 inhibition on improvement in cardiac function and remodeling in experimental models of myocardial infarction." (PMID 29669555, 2018). "Preclinical studies revealed that dipeptidyl peptidase (DPP4) inhibition is protective during myocardial infarction." (PMID 30087386, 2018). "Despite these mixed results in preclinical settings, it has been reported that DPP-4 inhibitors improve DD or long term survival in T2DM patients after acute myocardial infarction." (PMID 29669555, 2018). "After inducing myocardial infarction (MI), wild type (WT) and endoglin heterozygous (Eng+/-) mice were treated for 5 days with the DPP4 inhibitor Diprotin A (DipA)." (PMID 29253907, 2017). "This study aimed to evaluate the impact of DPP-4 inhibitors on the survival of diabetic patients after first acute myocardial infarction (AMI)." (PMID 28697774, 2017). "The rats after myocardial infarction (MI) exposed to sitagliptin, a dipeptidyl peptidase-4 inhibitor, led to attenuated sympathetic innervation probably through a phosphatidylinositol 3-kinase and Akt-dependent pathway." (PMID 26811539, 2016). "The improvement of cardiac function after myocardial infarction through a combination of DPP-4 inhibition and G-CSF administration has been reported, and liraglutide was able to confer cardioprotection and a survival advantage after myocardial infarction." (PMID 26937254, 2016). "In combination with G-CSF, DPP4 inhibition augments myocardial regeneration and improves cardiac function after myocardial infarction in mice." (PMID 26441982, 2015). "The stabilization of in vivo intact SDF1α by DPP4 inhibition can be a valuable therapeutic strategy after myocardial infarction." (PMID 26544044, 2015). "In the SITAGRAMI trial (NCT00650143), DPP4 inhibition in high doses was shown to increase the biological half-life of SDF1α and resulted in an improved cardial regeneration after myocardial infarction." (PMID 26544044, 2015). "In light of these effects in regulation of SDF-1, DPP4 inhibition has been suggested to be of potential benefit in cardiovascular diseases, such as myocardial infarction and peripheral artrerial disease." (PMID 26441982, 2015). "The endothelial DPP4 expression and activity were studied in human myocardial infarction in relation to a prothrombogenic endothelial phenotype." (PMID 23853775, 2013). "A previous study showed that genetic deletion or pharmacological inhibition of DPP4 improved cardiovascular outcomes following myocardial infarction in mice." (PMID 23359639, 2013). "Cardiac structure and function were assessed by hemodynamic monitoring and echocardiography in DPP4 knockout mice versus wild-type littermate controls and after left anterior descending coronary artery ligation-induced myocardial infarction." (PMID 23853775, 2013). "The effect of chemical inhibition or genetic deletion of DPP4 activity was studied on the cardiovascular function in normoglycemic and diabetic mice after experimental myocardial infarction." (PMID 23853775, 2013). "In experimental models of myocardial infarction, DPP4 inhibitors show cardioprotective effects." (PMID 41141478, 2025). "Polymorphisms in the DPP4 gene have been linked to T2DM and myocardial infarction." (PMID 40431452, 2025). "Moreover, inhibition of DPP4 gene products, which down-regulated DPP4a, decreased mortality after myocardial infarction in diabetic rats." (PMID 28587613, 2017). "Conversely, the role of DPP4 in myocardial infarction (MI) was largely consistent across studies." (PMID 28587613, 2017). "As a substrate of DPP-4, inhibition of SDF-1α degradation preserves its effects with considerable benefit in acute myocardial infarction, cardiac recovery after ischemia-reperfusion, or stroke." (PMID 39336583, 2024).
myocardial infarction (continued). "SDF-1α is a substrate of DPP4 enzyme and DPP4 inhibition preserves SDF-1α actions and promotes cardiac recovery after I/R, acute myocardial infarction, or stroke." (PMID 35945358, 2022). "Renal tubular and myocardial GLP-1R expression was increased by DPP-4 inhibition in CKD and acute myocardial infarction, supporting a correlation between inflammation and altered GLP-1R expression." (PMID 31795376, 2019). "Whereas a prior myocardial infarction significantly reduced pre-operative DDP4-activity, patients with preserved left ventricular function showed an intra-operative decrease of DPP4-activity." (PMID 30087386, 2018). "The cardiovascular safety and efficacy of sitagliptin, a dipeptidyl peptidase 4 (DPP-4) inhibitor, in type 2 diabetic patients after acute myocardial infarction (AMI) has so far remained uncertain." (PMID 26115092, 2015). "G-CSF administration in combination with DPP4 inhibitor leads to the stabilization of active SDF-1α, which attracted stem cells to the injury sites and improved outcome after myocardial infarction." (PMID 24416433, 2014). "Recent data suggest that PTH inhibits DPP4, leading to an increased concentration of plasma SDF-1α and favoring the homing of bone-marrow-derived CXCR4+ EPCs to sites of experimental myocardial infarction in mice." (PMID 23853775, 2013). "G-CSF administration in combination with DPP4 inhibitor leads to the stabilization of active SDF-1, which attracted stem cells to the heart and improved outcome after myocardial infarction." (PMID 23359639, 2013). "In contrast to the wealth of animal studies focusing on DPP4 in inflammation and myocardial infarction, no data are available on the kinetics and clinical significance of DPP4 activity in patients undergoing cardiac surgery with CPB." (PMID 30087386, 2018). "It was shown that the treatment with DPP4 inhibitor sitagliptin improved cardiovascular outcomes after myocardial infarction in non-diabetic mice; similar results were also obtained in non-diabetic DPP4−/− mice." (PMID 28194113, 2017). "It has been known for several years that both GLP-1 receptor (GLP-1R) agonists and dipeptidyl peptidase-4 (DPP-4) inhibitors, which increase endogenous GLP-1, protect cardiomyocytes from acute ischaemic damage and promote functional recovery after experimental myocardial infarction (MI)." (PMID 27079193, 2016). "Genetically-modified mice that are lacking the DPP-4 enzyme had improved survival post-myocardial infarction; similar protection was observed in normal mice treated with sitagliptin." (PMID 23286208, 2013). "Dipeptidyl peptidase-4 (DPP4) is an important regulator of incretins and inflammation, and it is involved in the pathophysiological process of myocardial infarction (MI)." (PMID 28000723, 2016). "A previous study reported that coronary artery disease (CAD) patients with myocardial infarction (MI) have a decreased concentration of plasma DPP4 than CAD patients without MI11, and a second study reported that DPP4a decreased over the 4 months after patients experienced MI12." (PMID 28000723, 2016). "Lack of DPP4 activity acts to decrease myocardial infarct size, stabilize the cardiac electrophysiological state during myocardial ischemia, reduce ischemia/reperfusion injury, and prevent left ventricular remodeling after myocardial infarction." (PMID 24416433, 2014). "Further, DPP4 activity decreased during cardiac surgery with CPB, if not already decreased by a recent myocardial infarction or severely reduced LVEF." (PMID 30087386, 2018). "Indeed, GLP-1 receptor (GLP-1R) agonists and dipeptidyl peptidase-4 (DPP-4) inhibitors, which increase endogenous GLP-1, are widely reported to protect cardiomyocytes from acute ischemia and improve functional recovery after myocardial infarction (MI)." (PMID 26597728, 2016).
myocardial infarction (continued). "In addition, the evidence from some clinical studies supporting a positive effect in the setting of myocardial infarction and percutaneous coronary revascularization represents an important challenge for the expansion of GLP-1 RA e DPP4-i therapeutics in non-diabetic patients other than diabetics." (PMID 37514043, 2023).
breast carcinoma (68 papers, 2013 to 2025). "Next, we analyzed the key molecules associated with DPP-4 inhibition-induced breast cancer metastasis in our previous study." (PMID 37760498, 2023). "Taken together, these results indicate that metformin can attenuate DPP-4 deficiency-induced breast cancer autophagy and survival through suppression of the mTOR/HIF-1α pathway." (PMID 37760498, 2023). "Here, we report that DPP-4 deficiency promotes breast cancer cell survival via the induction of autophagy by the C-X-C motif chemokine 12 (CXCL12)/C-X-C receptor 4 (CXCR4)/mammalian target of rapamycin (mTOR)/hypoxia inducible factor (HIF)-1α axis." (PMID 37760498, 2023). "In the current report, we focused on the pathological importance of DPP-4 deficiency in breast cancer autophagy." (PMID 37760498, 2023). "High expression levels of DPP3 and DPP4 were associated with poor survival of breast cancer patients, whereas high expression levels of DPP6, DPP7, DPP8, and DPP9 were associated with good prognoses." (PMID 34359286, 2021). "Here, we hypothesize that the CXCL12/CXCR4/mTOR/HIF-1α axis in DPP-4-deficient cells plays a key role in the activation of autophagy in breast cancer cells to promote survival." (PMID 37760498, 2023). "Finally, we found that the metformin-induced apoptosis of DPP-4-deficient 4T1 mammary cancer cells was associated with the suppression of autophagy." (PMID 37760498, 2023). "DPP-4 deficiency breast cancer cells treated with chemotherapy promoted the expression of snail." (PMID 31991851, 2020). "Moreover, we have reported that a DPP-4 inhibitor and shRNA-mediated DPP-4 knockdown both increases the expression of phosphorylated S6K in the primary tumors of 4T1 mammary tumor-bearing mice; metformin significantly repressed such a DPP-4 deficiency-induced mTORC1 pathway in vivo as well." (PMID 37760498, 2023). "Thus, the expression of CORO1A and ANXA5 may serve as the potential diagnostic indicators in breast cancer, and DPP4 might play a significant role in the tumorigenesis and progression of prostate cancer." (PMID 33407865, 2021). "The regulation and source of DPP4 in the breast cancer microenvironment after chemotherapy were still unclear." (PMID 40708008, 2025). "Based on proteome data of the breast cancer cohort, tumors sensitive to chemotherapy expressed higher levels of DPP4, indicating less ability to degrade sICOSL." (PMID 40708008, 2025). "Consistently, EZH2 inhibitors also blockaded H3K27me3 and induced re-expression of DPP4, which was initially suppressed by paclitaxel in breast cancer cell lines." (PMID 40708008, 2025). "We screened 29 regulators (11 positive and 18 negative) and verified them using correlation analysis between these genes and DPP4 in breast cancer cohort." (PMID 40708008, 2025). "Given that DPP4 is the key degradation enzyme of sICOSL, we created a genetic fusion of DPP4 enzymes and antibodies targeting cell-surface receptor of breast cancer." (PMID 40708008, 2025). "To assess the cytotoxicity of nanobody-DPP4 fusions, we treated breast cancer cells with varying HER2 expression levels with nanobody-DPP4 fusions in vitro." (PMID 40708008, 2025). "In the other hand, In the other hand, compared to control cancer cells, in paclitaxel-resistant breast cancer, the H3K27me3 level at the DPP4 transcriptional start site (TSS) was higher, silencing DPP4 expression." (PMID 40708008, 2025). "The study included comparisons to DPP-4 inhibitors, with similar neutral findings regarding breast cancer." (PMID 39595655, 2024). "Our recent study showed that metformin mitigates DPP-4 suppression-induced breast cancer growth and metastasis by mTOR regulation." (PMID 37760498, 2023). "In this paper, we reported that DPP-4 inhibition promotes breast cancer cell survival via induction of autophagy by the C-X-C motif chemokine 12/C-X-C receptor 4/mammalian target of rapamycin/hypoxia-inducible factor-1α axis." (PMID 37760498, 2023).